CST5 (cystatin D)
Description:
Cysteine proteinase inhibitor that possibly plays a protective role against proteinases present in the oral cavity. The order of preference for inhibition is cathepsin S > cathepsin H > cathepsin L > cathepsin B.
Tractability: Antibody: UniProt places it where antibodies can reach, with high confidence; its Gene Ontology location is reachable by antibodies, with high confidence; UniProt predicts a signal peptide or a membrane-spanning region.
Gene: Protein-coding gene on chromosome 20 (23,875,934 to 23,880,081, reverse strand). Ensembl gene ENSG00000170367.
Subcellular location: Secreted
Gene Ontology:
Molecular function: cysteine-type endopeptidase inhibitor activity; protein binding
Cellular component: extracellular exosome; extracellular region; cytoplasm; vesicle
Genetic constraint (gnomAD): Loss-of-function variants: 13 observed, 10.83 expected, observed/expected ratio (o/e) 1.2, 90% interval 0.78 to 1.8. The upper end of that interval is the gene's LOEUF score, 1.8, which puts it in group 6 of 6, group 1 being the genes least tolerant of losing a copy. Missense variants: 192 observed, 152.79 expected, observed/expected ratio (o/e) 1.26, 90% interval 1.12 to 1.42. Synonymous variants: 71 observed, 62.22 expected, observed/expected ratio (o/e) 1.14, 90% interval 0.94 to 1.39.
Homologues: Orthologues: chimpanzee CST5 (97% identical), macaque CST5 (85% identical), Caenorhabditis elegans cpi-1 (21% identical), Caenorhabditis elegans cpi-2 (20% identical), zebrafish si:busm1-57f23.1 (19% identical), Caenorhabditis elegans K08B4.7 (8% identical). Paralogues in human: CST2 (56% identical), CST1 (55% identical), CST4 (55% identical), CST3 (51% identical), CST6 (27% identical), CST11 (25% identical), CST7 (25% identical), CST8 (25% identical), CSTL1 (25% identical), CST9L (23% identical), CST9 (20% identical).
Diseases named in the same sentence as CST5 in open-access papers:
CST5 is named in the same sentence as 46 diseases in open-access papers, as found by Europe PMC text mining. Sharing a sentence is not in itself a finding about the gene and the disease. The quoted sentences say what the papers report.
colon carcinoma (7 papers, 2015 to 2024). "Accordingly, cystatin D and E-cadherin protein expression directly correlate in colon cancer, and loss of cystatin D is associated with poor tumor differentiation." (PMID 35406059, 2022). "The transcription of the CST5 gene, encoding cystatin D, is strongly induced by 1,25(OH)2D3 in colon carcinoma cells via direct binding of VDR to its promoter region." (PMID 32854355, 2020). "Researchers have observed that the expression of CST5 in human colon cancer cells is the opposite of CDCP1, significantly reducing the tumorigenic potential in immunodeficient mice." (PMID 39497803, 2024). "Our data supporting a suppressive effect by cystatin D on leukemia cell proliferation agree well with a study on colon carcinoma cells, demonstrating that cystatin D has tumor suppressor activity in this cell type." (PMID 32810913, 2020). "We found that cystatin D mediates the antiproliferative and prodifferentiation action of 1,25(OH)2D3 in human colon cancer cells." (PMID 26880977, 2016). "Recently, CST5 was shown to be induced by vitamin D3 via direct binding of the vitamin D receptor (VDR) to its promoter in human colon cancer cell lines." (PMID 26158294, 2015). "Cystatin D presumably plays an important role as a mediator of tumor suppression in colon cancer cells and is directly induced by the VDR." (PMID 26158294, 2015). "Moreover, cystatin D antagonizes the Wnt/β-catenin pathway and inhibits colon carcinoma cell proliferation and migration." (PMID 32854355, 2020). "In addition, ectopic cystatin D expression inhibits proliferation, migration, anchorage-independent growth, and the Wnt/β-catenin pathway in cultured colon cancer cells and reduces tumor development in xenografted mice." (PMID 26880977, 2016). "Furthermore, CST5 expression negatively correlates with human colon cancer progression emphasizing its potential tumor suppressive role for colorectal cancer." (PMID 26158294, 2015). "Notably, CST5 expression decreases during human colon cancer progression." (PMID 26158294, 2015).
brain injury (4 papers, 2017 to 2026). Acute and chronic (see also brain INJURIES, CHRONIC) injuries to the brain, including the cerebral hemispheres, CEREBELLUM, and brain STEM. "Interestingly, CST5 has also been shown to rise very early in blood after traumatic brain injury and has been proposed as an early inflammatory biomarker of brain damage." (PMID 41501840, 2026). "Recently, serum CST5 was identified as a promising early marker for traumatic brain injury." (PMID 33224151, 2020). "We conclude that CST5, AXIN1 and TRAIL are worthy of further study in the context of a pre-hospital or pitch-side test to detect brain injury." (PMID 28694499, 2017).
colorectal cancer (4 papers, 2015 to 2025). A primary or metastatic malignant neoplasm that affects the colon or rectum. "Accordingly, cystatin D and E-cadherin protein expression directly correlate in human colorectal cancer, and loss of cystatin D is associated with poor tumor differentiation." (PMID 26880977, 2016). "Recently, the active metabolite of vitamin D3, calcitriol (1,25(OH)2D3), was shown to induce CST5 expression in colorectal cancer cells." (PMID 26158294, 2015). "In colorectal cancer (CRC) cells CST5 was shown to mediate mesenchymal-epithelial transition (MET)." (PMID 26158294, 2015). "Recently, calcitriol-induced expression of cystatin D (CST5) was shown to inhibit proliferation, migration, anchorage-independent growth as well as tumor formation of xenografted colorectal cancer cell lines." (PMID 26158294, 2015).
COVID-19 (4 papers, 2020 to 2025). A disease caused by infection with severe acute respiratory syndrome coronavirus 2. "After adjustment for confounding factors, seven proteins that were highly abundant and associated with an increased hazard of critical COVID-19 outcome were SLAMF1, CCL25, IL2RB, IL10RA, IL15RA, IL18 and CST5." (PMID 40475767, 2025). "In random forest models for COVID-19, CST5, DPP7, NADK, KYAT1 and TYMP showed the highest variable importance." (PMID 35967328, 2022). "The cysteine proteinase inhibitor CST5 was the protein that showed the greatest downregulation in COVID-19." (PMID 35967328, 2022). "Levels of SLAMF1, CCL25, IL2RB, IL10RA, IL15RA, IL18 and CST5 were significantly upregulated in patients with critical COVID-19 illness compared to individuals negative for COVID-19." (PMID 40475767, 2025). "CST5 (adjusted fold change (FC)=0.065, p value<0.001), SRPK2 (adjusted FC=0.664, p value=0.003) and TGF-α (adjusted FC=0.647, p value=0.026) showed lower levels in COVID-19 patients." (PMID 35967328, 2022). "After adjusting for confounding factors, CST5, NADK, SRPK2 and TGF-α were differentially detected in COVID-19 and non-COVID-19 patients." (PMID 35967328, 2022).
Sepsis (3 papers, 2024). Sepsis is defined as life-threatening organ dysfunction caused by a dysregulated host response to infection. "T-cell surface glycoprotein CD6 isoform levels (CD6) (OR = 0.858, 95% CI = 0.737 ~ 0.999, P = 0.049) and Cystatin D levels (OR = 0.808, 95% CI = 0.695 ~ 0.940, P = 0.006) were associated with a decreased risk of sepsis (28-day mortality)." (PMID 39176264, 2024). "Similarly, the morphological parameter SSC-A on B-cells was associated with increased levels of cystatin D, which also contributes to deceased sepsis mortality." (PMID 39076981, 2024). "Currently, there is a dearth of studies on N-formylmethionine levels, cystatin D levels, ketogluconate metabolism and N10-formyl-tetrahydrofolate biosynthesis in patients with AN or sepsis." (PMID 38827616, 2024). "Additionally, mediation MR analysis indicated that blood N-formylmethionine levels and cystatin D levels accompanied by ketogluconate metabolism and N10-formyl-tetrahydrofolate biosynthesis in gut microbiome may mediate the causal connection between AN and sepsis." (PMID 38827616, 2024). "A large Mendelian randomized study found a negative association between CST5 and various immune-related diseases such as gout, IgA nephropathy, primary sclerosing cholangitis, and sepsis." (PMID 38827616, 2024). "In addition, N-formylmethionine levels, cystatin D levels, ketogluconate metabolism and N10-formyl-tetrahydrofolate biosynthesis may function as potential mediators in the pathophysiology of AN-sepsis." (PMID 38827616, 2024). "Mediation analysis indicated N-formylmethionine levels (with a mediated proportion of 7.47%), cystatin D levels (2.97%), ketogluconate Metabolism (17.41%) and N10-formyl-tetrahydrofolate biosynthesis (20.06%) might serve as mediators in the pathogenesis of AN-sepsis." (PMID 38827616, 2024). "There are few studies on the elaboration and role of cystatin D, and no relevant studies have reported the relationship among B cells, cystatin D and sepsis." (PMID 39076981, 2024).
injury (2 papers, 2018 to 2022). Damage inflicted on the body as the direct or indirect result of an external force, with or without disruption of structural continuity. "Circulating concentrations of CST5, an early biomarker for traumatic brain injury, were significantly increased in PLHIV with psychiatric conditions (pvalue<0.005)." (PMID 36157576, 2022).
acute myocardial infarction (1 paper, 2024). Necrosis of the myocardium, as a result of interruption of the blood supply to the area. "Furthermore, CST5 has emerged as a significant correlate of 28-day mortality post-acute myocardial infarction." (PMID 38703294, 2024).
Allergy (1 paper, 2025). An allergy is an immune response or reaction to substances that are usually not harmful. "For oncostatin-M (OSM), cystatin D (CST5) and hepatocyte growth factor (HGF) similar changes between visits were observed in both allergy groups." (PMID 40929127, 2025).
autism spectrum disorder (1 paper, 2022). A spectrum of developmental disorders that includes autism, and Asperger syndrome. "Although the effect of psychological stress on cystatin D has not been demonstrated so far, a decrease in the level of this protein in saliva was observed in a group of central nerve disorders, including neurodevelopmental and autism spectrum disorders." (PMID 35613108, 2022).
bladder cancers (1 paper, 2022).
cyst (1 paper, 2020). A sac-like closed membranous structure that may be empty or contain fluid or amorphous material. "This analysis yielded an inventory of previously undescribed cyst wall proteins (CST2/GRA50, CST3/GRA51, CST4, CST5/GRA52, and CST6/GRA53) that were validated to localize to the cyst wall by immunofluorescence." (PMID 32019789, 2020). "For example, proteins CST3, CST5, CST6, CST7, GRA3, and GRA14 were detected in the cyst wall proteome but not within the interactome." (PMID 32019789, 2020).
depression (1 paper, 2019). "The levels of several inflammatory molecules, including NGFs, IL-18, and CST5, were altered in the plasma of patients with depression." (PMID 31817800, 2019).
diabetes (1 paper, 2024). "Recent investigations, including a comprehensive German diabetes study encompassing both type 1 and type 2 diabetic patients, have revealed an inverse correlation between CST5 levels and estimated glomerular filtration rate (eGFR), positing a potential role for cystatin D in CKD progression." (PMID 38703294, 2024).
gastric cancer (1 paper, 2025). A primary or metastatic malignant neoplasm involving the stomach. "In contrast to previous reports of CST4 and CST5 being upregulated in gastric cancer tissue and serum, our study found both proteins to be significantly downregulated in saliva samples from GC patients." (PMID 41164825, 2025). "Our findings demonstrate that salivary proteins, particularly S100A8, S100A9, CST4, and CST5, hold significant potential as non-invasive biomarkers for gastric cancer detection." (PMID 41164825, 2025).
Gingival bleeding (1 paper, 2025). Hemorrhage affecting the gingiva. "Pregnant women with obesity and generalized gingival bleeding exhibited notably higher expression of Cystatin-D (>4-fold), with slight increases in Cystatin-B (1.62-fold), Cystatin-C (1.49-fold), and Cystatin-SN (1.12-fold) compared with G2." (PMID 40366920, 2025).
glioblastoma (1 paper, 2024). The most malignant astrocytic tumor (WHO grade IV). "Among the various factors examined, Cystatin D exhibited a positive correlation with the risk of glioblastoma (Odds ratio [OR], 1.27; 95% confidence interval [CI]: 1.06–1.52; p = 0.01) when utilizing inverse variance weighted (IVW) methods." (PMID 38784036, 2024). "Pathway and functional enrichment analyses suggested that Cystatin D might exert its effects on glioblastoma through intracellular protein transport, whereas FGF21 might affect glioblastoma via glucose response mechanisms." (PMID 38784036, 2024). "To investigate the role of Cystatin D, FGF21, IL-33 and CXCL9 in glioblastoma, we analyzed the correlation between the expression of these genes and survival prognosis characteristics in patients with glioblastoma." (PMID 38784036, 2024). "However, despite similar associations observed in other analyses, no causal effects of Cystatin D and FGF21 on glioblastoma were identified (p > 0.05)." (PMID 38784036, 2024). "Therefore, Cystatin D and FGF21 may influence the occurrence of glioblastoma through the brain-oral or brain-liver axes." (PMID 38784036, 2024). "Although the secretion of Cystatin D and FGF21 is not directly related to glioblastoma and its associated infiltrating immune cells, recent research has found that both the brain-liver axis and the brain-oral axis can have an impact on the central nervous system." (PMID 38784036, 2024). "Furthermore, elevated CST5 expression did not affect the OS of glioblastoma patients." (PMID 38784036, 2024).
keratoconus (1 paper, 2026). A degenerative, structural disorder of the eye, characterized by a cone-shaped protrusion of the cornea. "Cystatins (CST2, CST3, CST5), key inhibitors of cysteine proteases, were also decreased, potentially contributing to increased proteolytic activity and stromal degradation—an established pathogenic mechanism in keratoconus." (PMID 41601845, 2026).
leukemia (1 paper, 2020). A malignant (clonal) hematologic disorder, involving hematopoietic stem cells and characterized by the presence of primitive or atypical myeloid or lymphoid cells in the bone marrow and the blood. "Like cystatin D in the leukemia cells studied here, cystatin E/M was not expressed in the melanoma cells." (PMID 32810913, 2020).
liver cancer (1 paper, 2024). An epithelial or non-epithelial malignant neoplasm that arises from the liver. "However, in hepatitis B virus-related liver cancer, the levels of CST5 in tumors are lower than in normal tissues." (PMID 39497803, 2024).
liver diseases (1 paper, 2024). "Our analysis results show that CST5 is also a risk factor for disease progression in ALD, suggesting that the role and mechanisms of CST5 may vary in different organs, and it may play a detrimental role in liver diseases." (PMID 39497803, 2024).
lung adenocarcinoma (1 paper, 2025). A carcinoma that arises from the lung and is characterized by the presence of malignant glandular epithelial cells. "After outlier removal, significant heterogeneity was resolved for both the association between Cystatin D and lung adenocarcinoma (Q = 10.052, p = 0.122) and between cystatin M (prot‐a‐703) and squamous cell lung carcinoma (Q = 10.134, p = 0.256)." (PMID 40641363, 2025). "After the removal of outliers, the association between Cystatin D and lung adenocarcinoma turned significant (OR = 1.178, 95% CI: 1.023–1.358, p = 0.023)." (PMID 40641363, 2025). "This Mendelian randomization study revealed a causal association between genetically predicted cystatin 8 and squamous cell lung carcinoma, while Cystatin D was linked to lung adenocarcinoma after outlier adjustment." (PMID 40641363, 2025). "Notably, our findings revealed that Cystatin D plasma levels were causally associated with lung adenocarcinoma risk after outlier removal." (PMID 40641363, 2025). "Moreover, the initial MR analysis revealed heterogeneity for the associations between Cystatin D and lung adenocarcinoma, Cystatin M (prot‐a‐703) and squamous cell lung carcinoma, and Cystatin F and NSCLC." (PMID 40641363, 2025). "In the two‐sample MR analysis, the IVW analysis revealed positive causal associations between genetically predicted Cystatin 8 and squamous cell lung carcinoma, and cystatin D and lung adenocarcinoma after outlier removal." (PMID 40641363, 2025). "Significant heterogeneity was noted in the relationships between Cystatin D and lung adenocarcinoma (Q = 33.837, p < 0.001), Cystatin M (prot‐a‐703), and squamous cell lung carcinoma (Q = 25.73, p = 0.002), and Cystatin F and NSCLC (Q = 22.881, p = 0.029)." (PMID 40641363, 2025). "However, horizontal pleiotropy was noted between cystatin D and lung adenocarcinoma (global p < 0.001) and between cystatin M (prot‐a‐703) and squamous cell lung carcinoma (global p = 0.001) using MR‐PRESSO global test." (PMID 40641363, 2025).
lung carcinoma (1 paper, 2025). "For example, Cystatin D has been implicated in tumor suppression by inducing mesenchymal–epithelial transition and regulating immune responses, even though direct evidence linking Cystatin D and lung cancer was lacking." (PMID 40641363, 2025).
mastocytosis (1 paper, 2023). A clonal myeloproliferative neoplasm characterized by the proliferation and accumulation of neoplastic mast cells in one or multiple organs or organ systems. "The ability of cystatin D to regulate cytokine expression and secretion could be of great interest in the field of mastocytosis research, since several cytokines have been suggested as candidate diagnostic biomarkers and therapeutic targets." (PMID 37834061, 2023).
osteoporosis (1 paper, 2019). A condition of reduced bone mass, with decreased cortical thickness and a decrease in the number and size of the trabeculae of cancellous bone (but normal chemical composition), resulting in increased fracture incidence. "Here, we aim at exploring the effect of CST5 on bone resorption and activation of osteoclasts in osteoporosis (OP) rats through the NF‐κB pathway." (PMID 31402549, 2019).